CREB1 (cAMP responsive element binding protein 1)
Diseases named in the same sentence as CREB1 in open-access papers (continued):
Sharing a sentence is not in itself a finding about the gene and the disease.
tumor (continued). "Furthermore, 10 of these 26 (38.5%) patients had a tumor with an EWSR1::ATF1 fusion, eight (30.8%) had EWSR1::CREB1 fusion, six (23.1%) had EWSR1::CREM, one (3.8%) had EWSR1::CREB3L3, and one (3.8%) had FUS::CREM fusion." (PMID 38291529, 2024). "CRIP1 and CREB1 mediated secretion of VEGFC and CCL5 could then reshape the tumor microenvironment into a suitable “soil” which favor lymphangiogenesis and LM in GC." (PMID 37409440, 2023). "Our data also suggest that transcription factors such as CREB1 and ESR1 as well as pioneer factors such as PU.1 and Sp1 may contribute to the differentiation of MDSCs in the tumor." (PMID 36480485, 2022). "As a tumor suppressor, miR-433 strongly inhibits MHCC97H cell migration by targeting CREB1." (PMID 35255830, 2022). "Although the major biological function of PTEN is to dephosphorylate lipid substrates, it has also been reported to dephosphorylate protein substrates, including cAMP-responsive element-binding protein 1 (CREB1) and insulin receptor substrate 1 (IRS1) to perform its tumor-suppressive function." (PMID 36336681, 2022). "Our analysis obtained 29 top-ranked upregulated genes, which are further displayed with no. of tumor occurrence and their average expression fold change of CREB1 Rescue vs KO." (PMID 34641874, 2021). "MIR27B is a well-validated tumor suppressor and mechanistically modulates critical oncogenic molecules such as the nuclear receptor subfamily 5 group A member 2 gene (NR5A2) and response element-binding protein (CREB1)." (PMID 33920789, 2021). "Analyzing 453 consecutive RCC tumors by immunohistochemistry, weakly negative, but significant correlations of CREB1 with tumor stage and grade, vascular invasion (V1) and lymphovascular invasion (L1) were found." (PMID 32300145, 2020). "Univariate analysis revealed that tumor depth, lymph node invasion, distant metastasis, pTNM stage, CEA, CA19-9, CREB1, CCAR1 and JNK1 may act as potential prognosticators." (PMID 30523220, 2018). "From the point of view of cancer or tumor research, it was reported that miR-103 is part of the G1/S transition regulatory network, by targeting CCNE1, CDK2, and CREB1 (cAMP responsive element binding protein 1) during IGF-1 simulated proliferation in mouse crypt cells." (PMID 26935418, 2016). "The mouse xenograft model was also used to evaluate whether knockdown of EMP2 and double knockdown of CREB1 and EMP2 affected tumor growth in vivo." (PMID 25940704, 2015). "Additionally, the in vivo assays revealed the inhibitory impact of LINC00665_18aa on xenograft tumor growth, which is lacking the evidence about the involvement of CREB1/RSK2 interaction in the regulation of LINC00665_18aa." (PMID 37285335, 2023). "Mechanistically, imperatorin can directly bind with CREB1 and inhibits its phosphorylation and interaction with TGFβ2 promoter, then inactivates extracellular signal‐regulated kinases (ERK) signaling and fibroblasts‐secreted CCL2 to block tumor angiogenesis and metastasis." (PMID 32832354, 2020). "CREB1 RNA was not DE between virus-positive and virus-negative tumours, however, its asRNA, AC007879.5, was significantly downregulated in HPV16+ tumours." (PMID 29263803, 2016). "CREB1 and CTSL1 were slightly overexpressed but not statistically significant, while PSME3 showed a significantly reduced level in RCC tumor tissues." (PMID 25784652, 2015). "Therapeutic selection was guided by molecular profiling and tumour characteristics, particularly the NGS results from liver and peritoneal metastases, which revealed: PD-L1 expression of 15%, presence of the EWSR1/CREB1 fusion, no other actionable oncogenic drivers, and a Ki-67 index of 30%." (PMID 41020828, 2025). "However, imperatorin could not suppress the ability of CREB1‐knockout cells to form tumor metastasis, and more importantly, the anti‐metastatic effect of imperatorin was recovered when the cells were re‐overexpressed with wild‐type CREB1, but not the mutant CREB1." (PMID 32832354, 2020).
cancer (392 papers, 2008 to 2026). A tumor composed of atypical neoplastic, often pleomorphic cells that invade other tissues. "Combined mitochondrial and nuclear targets of ATF1/CREB1 is associated with worse prognosis in cancer patients from the TCGA and GEO datasets compared with either mitochondrial or nuclear subset of targets." (PMID 37463926, 2023). "cAMP response element (CRE)‐binding protein 1 (CREB1) is a master transcription factor that can function as a proto‐oncogene, the abnormal activity of which is associated with multiple cancers." (PMID 37565725, 2023). "Overexpression of CREB1 is often found in multiple human cancers and linked to several hallmarks of cancer." (PMID 37565725, 2023). "CREB1 is a transcription factor implicated in neuronal survival and constitutively expressed in different types of human cancer." (PMID 35241647, 2022). "In these types of cancer deregulation of CREB1 was shown to be associated with enhanced proliferation, reduced apoptosis and increased angiogenesis." (PMID 32300145, 2020). "Dysregulation of CREB1 has been implicated in various types of cancer including BC." (PMID 38008726, 2023). "Moreover, numerous studies reported that CREB1 overexpression is associated with epithelial–mesenchymal transition (EMT) of cancer cells in a variety of cancers." (PMID 35096015, 2021). "CREB-1 has been implicated in multiple human cancers as well as diverse cellular processes." (PMID 24423398, 2013). "The overexpression of TCEAL2 in cancer condition was observed in our GSE54129 dataset, meanwhile the loss of negative regulation of TCEAL2 by CREB1 in cancer was inferred, which may facilitate proliferation and inhibit apoptosis and thus promotes carcinogenesis." (PMID 35421923, 2022). "Indeed, CREB1 is a well-known regulator of glycolytic enzymes hexokinase and lactate dehydrogenase and has recently been shown to be involved in aerobic glycolysis induction in cancer-associated fibroblasts." (PMID 29614062, 2018). "Mechanistically, DAG upregulates TGF-β1 expression through PKC-mediated enhancement of CREB1 phosphorylation in multiple TNBC cell lines, directly promoting TNBC progression and activating cancer-associated fibroblasts." (PMID 41862453, 2026). "CAMK1G has been shown to phosphorylate the transcription factor CREB1, which plays a key role in promoting cancer development and progression by enhancing cellular plasticity and driving metabolic reprogramming." (PMID 40832614, 2025). "Numerous studies have demonstrated that CREB1 exerts control over the growth and invasion of cancer cells, nerve cells, vascular endothelial cells, and immunized T cells." (PMID 38473754, 2024). "The transcription factor CREB1 is also upregulated in PCa determining cancer-relevant cell cycle, pro-survival and metabolic gene expression patterns associated with poor clinical outcomes." (PMID 39337607, 2024). "During our studies we noticed that the depletion of CREB1 in the HPV+ cancer lines decreased E6 and E7 expression." (PMID 37565725, 2023). "Here, we showed that the transcription of HPV early genes was upregulated by CREB1 in cancer cell lines and in primary keratinocytes harboring the entire HPV18 genome." (PMID 37565725, 2023). "Activation of CREB1 by phosphorylation is known to contribute to increased growth and survival of cancer cells." (PMID 37172090, 2023). "The shRNAs targeting ATF1 and CREB1 are consistently decreased in MDA-MB-231, NCI-H460 and DLD1 spheres, indicating impaired cancer stemness in ATF1/CREB1 deficient cells." (PMID 37463926, 2023). "In a study of therapeutics targeting cancers, mTOR activation triggered CREB1 phosphorylation and accumulation, and inhibiting CREB1 led to a decrease in ATG7, which is a key factor in autophagy regulation." (PMID 37947633, 2023).
cancer (continued). "First, the subinteractomes of these ORF proteins contain proteins associated with ‘cancer hallmark’ and oncoproteins (e.g., the case of C5orf24 and its protein partners XPO1, PBX1, MYC, CIC, GOPC, CREB1 and STK11)." (PMID 37373333, 2023). "According to the transcriptomic data from TCGA, the expression correlation between CREB1 and all 50 793 genes in 33 cancers was calculated using the R score." (PMID 36734611, 2023). "We examined the relationship between CREB1 expression and the ROS pathway activity across different cancer types." (PMID 37957645, 2023). "A major focus molecule was CREB1, which is a transcriptional factor for cell survival, cancer development, metastasis, and many other processes." (PMID 35216124, 2022). "Further studies are needed on the role of CREB1 and TNF signaling in MSS cancers and their susceptibility to immunotherapy." (PMID 36387154, 2022). "Many studies confirmed higher CREB1 expression in human ovarian adenocarcinoma and cancer cell lines." (PMID 36497095, 2022). "CREB1 modulates cancer progression through transcriptional regulation of microRNA and is a promising molecular target." (PMID 36522613, 2022). "The overexpression of MBNL1 was observed in our present dataset, in accordance with the emerging positive regulation of MBNL1 by CREB1 in cancer." (PMID 35421923, 2022). "As a transcription factor involved in metabolism and DNA repair, cAMP-responsive element-binding protein-1 (CREB1) has been proven to play a carcinogenic role in various cancers." (PMID 36522613, 2022). "CREB1 is a phosphorylation-dependent transcription factor frequently upregulated in human cancers, including HCC." (PMID 35769513, 2022). "Impairment of PKA function in platinum-resistant cells results in inhibition of CREB1 phosphorylation at Ser-133, which in turn decreases the survival of platinum-resistant cancer cells and inhibits the G2-M cell cycle." (PMID 36497095, 2022). "Other module genes belonged to TGF β signaling (e.g. FURIN and CREB1), a pathway identified already from the pairwise approach and involved in cancer drug resistance." (PMID 36043458, 2022). "Our systematic and integrative approach to decipher the CREB1-mediated gene network in cancer is an effective and powerful tool that can be applied in other transcription factor-related research." (PMID 34641874, 2021). "So a comprehensive and in-depth analysis of the gene network constitutively regulated by CREB1 can be necessary and important for understanding how CREB1 functions in cancer cells and providing a theoretical basis for tailored cancer therapies." (PMID 34641874, 2021). "To better describe these cancer-relevant CREB1 targeted genes, we further included intersection, fold change (CREB1 rescue cells vs corresponding CREB1 KO clone), and NO." (PMID 34641874, 2021). "This inference is also supported by the fact that the aberrant activation of the PI3K-Akt pathway and overexpression of CREB1 occurs simultaneously to promote the survival and proliferation in many human cancer cells." (PMID 34641874, 2021). "The cancer genomics (mutations, copy number variations, and mRNA levels) and patients’ survival data in these cancer types were analyzed for the role of CREB1." (PMID 33921660, 2021). "Taken together, our current work highlights the importance of the gene network constitutively regulated by CREB1 in cancer cells." (PMID 34641874, 2021). "In this study, we observed that the expression of CREB1 is dysregulated in pan-cancer, especially in OV." (PMID 33921660, 2021). "Contrary to the widely acknowledged essential role of CREB1 in cancers, a comprehensive and in-depth investigation of the gene network mediated by CREB1 is less explored." (PMID 34641874, 2021).
cancer (continued). "This pan-cancer analysis also indicated that CREB1 gene alterations occurred most frequently in OV, compared with other cancer types." (PMID 33921660, 2021). "To identify CREB1 target genes with potential cancer relevance, we combined genes exclusively intersected by all 4 lists and by lists 1, 2, 4 as the top-ranked genes." (PMID 34641874, 2021). "In this regard, we summarize the information about all top-ranked CREB1 targets that are reported as cancer biomarkers." (PMID 34641874, 2021). "We affirmed this inference by comparing the overall survival and hazard ratios of cancer patients with high and low expression of selected genes from the top-ranked CREB1 target list, meaning that our methodology is very reliable." (PMID 34641874, 2021). "To analyze the expression pattern of CREB1 in various cancers, we accessed the TCGA and GEPIA databases." (PMID 33921660, 2021). "To our knowledge, we are the first to establish the transcriptomic correlation between CREB1 and most of these essential cancer-relevant genes." (PMID 34641874, 2021). "Wilderness investigations manifested the involvement of CREB1 in multiplex signaling pathways relative to various cancer cells." (PMID 35096015, 2021). "The CREB1 is the only gene in common among the three cancer cell lines tested after the administration of the IS." (PMID 34157951, 2021). "Although CREB1 has been extensively studied in various tumors, CREB1 is aberrantly expressed in a variety of human cancers, including solid tumors and hematologic malignancies." (PMID 33921660, 2021). "We carried out the comparison of the transcriptional levels of CREB1 in cancers with those in the normal specimens through the use of ONCOMINE databases." (PMID 33921660, 2021). "To pinpoint CREB1 direct target genes with strong cancer relevance, we brought previous CREB1 Chipseq data into our analysis." (PMID 34641874, 2021). "We prepared the differentially expressed genes (DEGs) from CREB1-overexpressing different cancer cells and queried the CMap database." (PMID 33921660, 2021). "To investigate this complex gene network and identify essential CREB1 target genes with strong cancer relevance in a systematic manner, we designed and performed the present study." (PMID 34641874, 2021). "We further categorized CREB1-regulated genes into different groups according to Chiqseq, RNAseq, and RRHO analysis and confirmed the significances of several novel CREB1 target genes, whose expressions matter for the overall survival of cancer patients." (PMID 34641874, 2021). "Lastly, to evaluate the influence of these top-ranked CREB1 target genes over cancer development, we performed Kaplan–Meier analysis of cancer patient's overall survival." (PMID 34641874, 2021). "Accumulating evidence suggests that CREB1 promotes tumorigenesis and is overexpressed in numerous human cancers, including breast cancer, mesothelioma, ovarian cancer, and prostate cancer." (PMID 30674866, 2019). "As Creb1 dysregulation is likely to be involved in multiple neurological conditions and cancer metastasis, these results provide new insight into the importance of oxidative DNA damage and its repair." (PMID 31024003, 2019). "MAPKs (e.g., p38 and ERK) can phosphorylate and activate CREB-1, thereby promoting the pro-survival signaling that is important for cancer development and progression." (PMID 28534824, 2017). "CREB1, as a transcription factor, regulates many downstream genes and implicates in cell proliferation and motility in various cancers." (PMID 29137265, 2017).
cancer (continued). "Abnormal expression of CREB1 has been reported in a number of human cancers including solid tumors and hematological malignancy." (PMID 27801665, 2016). "Intriguingly, mounting evidence suggests that CREB1 has potentially oncogenic functions and plays critical roles during carcinogenesis and cancer progression." (PMID 25825983, 2015). "An increasing number of studies have shown that CREB1 was aberrantly expressed in a number of human cancers including both solid tumors and hematological malignancy." (PMID 25825983, 2015). "Although CREB1 has been shown to be aberrantly expressed in several human cancers, information about its regulation is relatively unclear." (PMID 25825983, 2015). "Nevertheless, the mechanism by which CREB-1 can regulate autophagy and pro-survival signals in cancer cells will require further studies." (PMID 26474850, 2015). "Among the numerous possible candidates, we picked out the ones overexpressed in cancers and proliferation- and metastasis-associated genes, including NOTCH2, FGFR1, CSF1, AGAP2, CREB1, for further analysis." (PMID 24614175, 2014). "Since the cells were cultured in serum-free medium containing bFGF and EGF, very likely these growth factors up-regulated the expression of kinases such as MSK-1 in a small subset of UM1 cancer cells (CSC-like cancer cells) and subsequently activated CREB-1." (PMID 24423398, 2013). "As a recognised cancer target, CREB1 is usually upregulated in cancer tissues." (PMID 40794013, 2025). "Furthermore, we analyzed the mutation status of ASCC3, JAK1, NFKB1, SEMA5A, NR2C2, CNTF and CREB1 across pan-cancer." (PMID 40881169, 2025). "Notably, PKA activation has been observed to promote platinum resistance in ovarian and other cancers, and CREB1 inhibition potently sensitized OvCa tumor cells to cisplatin." (PMID 38132444, 2023). "In OS, activation of CREB1 is crucial for cancer initiation and maintenance." (PMID 37285335, 2023). "Indeed, transcription factors binding cAMP responsive element (CRE) motif (ATF1 and CREB1) and CRE-like motif (AP1) are enriched in the oncospheres of multiple cancer types (7/11 and 6/11 of cancer types for ATF1/CREB1 and AP1, respectively)." (PMID 37463926, 2023). "Several studies have reported inconsistent effects of CREB1 on cancer cells and normal cells, which may explain the discrepancy between our results and those of other researchers." (PMID 37947633, 2023). "CREB1 functions as an oncogene in some cancers, such as CRC." (PMID 36313570, 2022). "CREB1 was considered to promote invasion and migration in human cancers, including NSCLC." (PMID 35193578, 2022). "In CRC, miR-383 can operate as a cancer suppressor by modulating CREB1 expression." (PMID 36313570, 2022). "This might be true, particularly in the context of tumors, as only a few CREB1 target genes essential for cancer cell survival, proliferation and metastasis have been identified and most of them are regulated in this manner." (PMID 34641874, 2021). "This is in agreement with our initial hypothesis, that CREB1 constitutively regulates a set of targets to promote cancer development in a cAMP-independent manner." (PMID 34641874, 2021). "First, we explored whether CREB1 is involved in multiple types of cancer and physiological functions." (PMID 33921660, 2021). "Moreover, some of these CREB1 targets are regarded as prognostic indicators and biomarkers for distinct types of cancer." (PMID 34641874, 2021). "Furthermore, it has been shown that several oncogenic miRNAs are activated by CREB1 transcriptionally, resulting in the facilitation of cancer development." (PMID 32280303, 2020). "Further, existing studies of cancers have reported that CREB1 could induce the transactivation of oncogenic miRNAs, such as miR-23a and miR-302a." (PMID 32280303, 2020).